RRM1 (ribonucleotide reductase catalytic subunit M1)
Diseases named in the same sentence as RRM1 in open-access papers (continued):
Sharing a sentence is not in itself a finding about the gene and the disease.
pancreatic cancer (continued). "We also carried out in vitro experiments to analyze the functional consequences of RRM1 expression, especially focusing on DNA damage in pancreatic cancer cells in response to gemcitabine exposure." (PMID 34111175, 2021). "And RRM1 protein expression was confirmed at various levels by Western blotting in the panel of pancreatic cancer cell lines." (PMID 34111175, 2021). "In the present study, we investigated RRM1 expression levels in pancreatic cancer by immunohistochemical staining of tumor sections and attempted to determine correlations with clinicopathological factors and survival." (PMID 34111175, 2021). "On the other hand, in pancreatic cancer with low RRM1, there was a trend toward a benefit from additional postoperative adjuvant chemotherapy comparing to no adjuvant group, although the difference was not statistically significant." (PMID 34111175, 2021). "Real time RT-PCR analysis demonstrated that RRM1 mRNA expression was aberrantly activated in all pancreatic cancer cell lines comparing to normal pancreas tissue." (PMID 34111175, 2021). "Numerous studies have indicated that hENT1, dCK and RRM1 are key proteins for gemcitabine resistance in pancreatic cancer." (PMID 30867652, 2019). "In pancreatic cancers, the overall evidence supporting the predictive effect of RRM1 was equivocal and investigated only in levels III-IV studies." (PMID 27888622, 2017). "As regulators of the cell cycle, RRM1 and RRM2 are associated with gemcitabine resistance in pancreatic cancer." (PMID 28797284, 2017). "RRM1 have been reported previously as predictive markers for gemcitabine in pancreatic cancer, although there are few published studies evaluating their value in BTC." (PMID 23710668, 2013). "Marechal and colleagues recently investigated the predictive value of hENT1, dCK, and RRM1 in patients with pancreatic cancer treated with adjuvant gemcitabine chemotherapy and demonstrated that both hENT1 and dCK expressions were powerful predictive markers." (PMID 23710668, 2013). "The hENT1 × dCK/RRM1 × RRM2 ratio significantly correlated with the gemcitabine IC50 in eight pancreatic cancer cell lines (P=0.0029)." (PMID 17224927, 2007). "Notably, PRNP showed the strongest positive correlation with RRM1 (Pearson’s R = 0.37, p < 0.05), supporting its prioritization as a potential therapeutic target for overcoming gemcitabine resistance in pancreatic cancer." (PMID 41394830, 2025). "Similarly, the protein levels of both SLC38A5 and RRM1 were increased in drug-resistant pancreatic cancer patients compared with those in the drug-sensitive group." (PMID 37887353, 2023). "RRM1 was found to be upregulated in gemcitabine-resistant pancreatic cancer cells." (PMID 36211828, 2022). "Cytoplasmic RRM1 activation is involved in biological processes related to drug resistance in response to gemcitabine exposure and could be a potential target for pancreatic cancer treatment." (PMID 34111175, 2021). "RRM1 alteration after gemcitabine exposure was then evaluated using 3 pancreatic cancer cell lines." (PMID 34111175, 2021). "Our results supported the hypothesis that RRM1 inhibition enhances the effect of gemcitabine, which could be useful for the treatment of pancreatic cancer." (PMID 34111175, 2021). "The clinical significance of RRM1 expression in pancreatic cancer cells was then evaluated." (PMID 34111175, 2021). "RRM1 has also been reported to affect disease prognosis of pancreatic cancer." (PMID 34111175, 2021). "Therefore, RRM1 expression probably affects overall survival than disease free survival in pancreatic cancer patients with adjuvant chemotherapy." (PMID 34111175, 2021). "Similarly, other genes amplified upon gemcitabine resistance in pancreatic cancer are RRM1 and STIM1." (PMID 33919156, 2021).
pancreatic cancer (continued). "For those pancreatic cancer patients with high RRM1 expression in their tumors, adjuvant chemotherapy with gemcitabine together with RRM1 inhibition might be an attractive treatment strategy leading to better postoperative outcomes." (PMID 34111175, 2021). "Furthermore, cytotoxic effects after gemcitabine exposure were significantly increased in pancreatic cancer cells on treatment with RRM1-specific siRNA, relative to controls in both MIAPaCa2 and PSN1 cells." (PMID 34111175, 2021). "In pancreatic cancer with high RRM1, there was little therapeutic effect of adjuvant chemotherapy." (PMID 34111175, 2021). "For example, upon gemcitabine resistance acquisition in pancreatic cancer as well as in non-small-cell lung carcinoma, an amplification of one of the main targets of gemcitabine, ribonucleotide reductase catalytic subunit M1 (RRM1), was observed." (PMID 33919156, 2021). "A recent meta-analysis revealed that patients with high RRM1 expression had largely poorer OS and DFS than those with low RRM1 expression, suggesting that the expression of RRM1 is an indicator of poor survival in patients with pancreatic cancer accepting gemcitabine chemotherapy." (PMID 31514451, 2019). "In pancreatic cancer, interestingly, RRM1 levels were inversely correlated with patient survival." (PMID 29983871, 2018). "Notably, in PANC-1 pancreatic cancer cells, overexpression of both RRM1 and RRM2 was found to be a necessary requirement for development of resistance to gemcitabine." (PMID 29144412, 2017). "RRM1 overexpression has been correlated with 5-fluorouracil resistance in pancreatic cancer." (PMID 23922955, 2013). "Several molecules involved in gemcitabine metabolism, including human equilibrative nucleoside transporter (hENT1), deoxycytidine kinase (dCK), and ribonucleotide reductase subunit M1 (RRM1), have been investigated as predictive biomarkers of gemcitabine efficacy, mostly in pancreatic cancer." (PMID 23710668, 2013). "Notably, RRM1-specific siRNA treatment downregulated cell viability of pancreatic cancer cells." (PMID 34111175, 2021). "However, the biological activity of RRM1 in pancreatic cancer remains undetermined." (PMID 34111175, 2021). "Our study provides evidence that RRM1 could be an effective target in pancreatic cancer treatment." (PMID 34111175, 2021). "In addition, downregulation of RRM1 or RRM2 in pancreatic cancer cells could increase their chemosensitivity to gemcitabine." (PMID 28797284, 2017). "Fasted pancreatic cancer cells showed increased levels of equilibrative nucleoside transporter (hENT1), the transporter of gemcitabine across the cell membrane, and decreased ribonucleotide reductase M1 (RRM1) levels as compared to those cultured in standard medium." (PMID 26176887, 2015). "More study on the interaction between RRM1 and MMP-3 in pancreatic cancer is urgently needed in the future." (PMID 36211828, 2022). "However, the functions of RRM1 in pancreatic cancer biology remain unclear." (PMID 34111175, 2021). "Experiments confirmed that overexpression of RRM1 and RRM2 proteins of the pancreatic cancer cell line can achieve stable genetic gemcitabine resistance." (PMID 31514451, 2019). "The expression of the main four factors (hENT1, dCK, RRM1 and RRM2) involved in gemcitabine transport and metabolism was also shown to correlate with acquired resistance to gemcitabine in pancreatic cancer cells." (PMID 31652737, 2019). "Previous studies have found that the expression of RRM1 and RRM2 in pancreatic cancer cells increases their sensitivity to gemcitabine." (PMID 28797284, 2017). "The drug resistance genes, RRM1 and RRM2, reduce the pharmacological activity of gemcitabine by affecting its metabolism in pancreatic cancer cells." (PMID 28797284, 2017). "Treatment of human pancreatic cancer cells with CBL0137 resulted in a dose dependent reduction of protein and mRNA levels of RRM1 and RRM2." (PMID 25402820, 2014).
pancreatic cancer (continued). "The transcriptional upregulation of RRM1 and RRM2 has been consistently observed in pancreatic tumors resistant to gemcitabine and pancreatic cancer cell lines." (PMID 25402820, 2014). "RRM1 overexpression is related to resistance to gemcitabine in NSCLC and pancreatic cancer, which results in a poor outcome." (PMID 23922955, 2013). "The potential predictive role of RRM1 and RRM2 mRNA expression warrants examination in malignancies where gemcitabine-based therapy is standard, such as pancreatic cancer." (PMID 18414411, 2008). "Furthermore, RRM1 alteration after gemcitabine exposure was significantly scant in PSN1 cells, which are gemcitabine-sensitive in pancreatic cancer cells lines." (PMID 34111175, 2021). "Our data demonstrate for the first time that acquired and inherent chemoresistance of pancreatic cancer cells to gemcitabine is determined by the balance of dCK, RRM1, RRM2, and hENT1 gene expression, but not to that of any of the individual genes." (PMID 17224927, 2007). "To determine whether the hENT1 × dCK/RRM1 × RRM2 ratio correlated with gemcitabine sensitivity, we examined the relative mRNA expression of hENT1, dCK, RRM1, and RRM2 to GAPDH in eight human pancreatic cancer cell lines." (PMID 17224927, 2007). "We derived several gemcitabine resistant subclones from the human pancreatic cancer cell line BxPC3 and determined that the observed chemoresistance was driven of a focal amplification of the chr11p15.4 genomic region, resulting in over-expression of the ribonucleotide reductase (RNR) subunit RRM1." (PMID 35617275, 2022). "Unfortunately, the regulation of RRM1 in pancreatic cancer is still not clear." (PMID 36211828, 2022). "We explored whether GA affects the expression of RRM1 and RRM2 in pancreatic cancer cells." (PMID 28797284, 2017). "In this regard, induction of the non-regulatory RRM1 subunit, expression of anti-apoptotic proteins, activation of cell survival genes, and induction of drug-efflux proteins (e.g., MRPs) have been shown to modulate gemcitabine chemosensitization in drug-resistant pancreatic cancer cells." (PMID 23335963, 2013). "RRM1 and ERCC1 expression does not seem to have a clear predictive or prognostic value in pancreatic cancer." (PMID 22436573, 2012).
non-small cell lung carcinoma (26 papers, 2006 to 2025). A group of at least three distinct histological types of lung cancer, including non-small cell squamous cell carcinoma, adenocarcinoma, and large cell carcinoma. "A meta-analysis of 23 studies on non-small cell lung cancer found that high levels of RRM1 significantly associated with a shorter OS of the patients, though the prognostic significance was not reached in Cox regression analysis." (PMID 38672281, 2024). "A SNP in the promoter region of Rrm1 gene was reported to be associated with progression free survival in non-small-cell lung cancer patients treated with gemcitabine-based chemotherapy." (PMID 24844776, 2014). "Furthermore, low expression of RRM1 is associated with a poor survival rate among patients with non-small-cell lung cancer (NSCLC)." (PMID 24926347, 2014). "We investigated whether RRM1 expression in peripheral blood mononuclear cells (PBMCs) or SNPs were associated with clinical outcome after gemcitabine-based chemotherapy in advanced non-small cell lung cancer (NSCLC) patients." (PMID 20226083, 2010). "It is also worth mentioning that not only the dNTP amount but also the NTP amount was reduced when RRM1 or RRM2 was knocked-down in the H23 non-small cell lung cancer cells." (PMID 37513740, 2023). "RRM1 staining correlated to general drug sensitivity of primary cells, comparable findings have been seen in non-small cell lung cancer patients treated with cisplatin and vinorelbine, where immunohistochemical evaluation of RRM1 predicted drug effect." (PMID 25253633, 2014). "Te aim of this study is to explore the relations between RRM1 protein expression levels and effects of gemcitabine and cisplatin chemotherapy in advanced non-small cell lung cancer (NSCLC) patients." (PMID 21496433, 2011). "In non-small cell lung cancer (NSCLC), GA improves sensitivity to cisplatin and gemcitabine by inhibiting the NF-κB and MAPK/HO-1 pathways, while reducing the expression of resistance-associated proteins such as MDR1 and RRM1." (PMID 41311720, 2025). "High expression of RRM1 can lead to poor prognosis in patients with non-small cell lung cancer." (PMID 36973651, 2023). "Also, RRM1 was correlated with expression of the DNA repair protein ERCC1 and was associated with better outcome of early-stage non-small-cell lung cancer." (PMID 23922955, 2013). "Finally, non-small cell lung cancer patients with low level expression of the Ml subunit of RR (RRM1) significantly benefited from gemcitabine/cisplatin neoadjuvant chemotherapy, while resistance to gemcitabine was observed in cells overexpressing both RRM1 and RRM2." (PMID 24504118, 2014). "In tumor specimens from 187 patients with non-small-cell lung cancer, total CHK1 and RRM1 in situ protein levels were significantly (p = 0.003) and inversely correlated." (PMID 23483975, 2013). "We have retrospectively examined the effect of RRM1, RRM2 and BRCA1 expression on outcome to gemcitabine plus docetaxel in advanced non-small-cell lung cancer (NSCLC) patients." (PMID 19002265, 2008). "Finally, non-small cell lung cancer patients with low expression of the M1 subunit of RR (RRM1) significantly benefited from gemcitabine/cisplatin neoadjuvant chemotherapy, while resistance to gemcitabine was observed both in RRM1 and RRM2 overexpressing cells." (PMID 16868547, 2006). "Moreover, RRM1 has been reported as a biomarker of treatment response in several neoplasms, such as MPM, non-small cell lung cancer and pancreatic adenocarcinoma; however, results from these studies are not conclusive about the role of RRM1 as a biomarker for treatment response in patients with MPM." (PMID 34353292, 2021).
breast carcinoma (15 papers, 2010 to 2024). "Overexpression of RRM1 has been linked to chemoresistance in breast cancer, as it supports DNA replication in rapidly dividing tumor cells and promotes survival under genotoxic stress." (PMID 39596229, 2024). "Nine genes in this module – Akt1, Brca2, Ccnd1, Dnmt1, Mki67, Palb2, Rrm1, Timeless, and Top2a – are known human breast cancer genes according to the MalaCards database; four of them are hub genes." (PMID 28212608, 2017). "The models included genetically RRM1-modified lung and breast cancer cell lines, cell lines with gemcitabine-induced RRM1 overexpression, and a series of naturally gemcitabine-resistant cell lines." (PMID 23483975, 2013). "Differences in methodologies, chemotherapy regimens, and cancer type do compromise the comparability of studies, and the prognostic significance of RRM1 in advanced breast cancer remains to be further elucidated." (PMID 24215511, 2013). "Gemcitabine sensitivity has been associated with RRM1 A2464A in vitro, but no similar result has been observed in breast cancer patients." (PMID 20226083, 2010). "RR has two subunits, M1 (RRM1) and M2 (RRM2), and the latter is overexpressed in human breast carcinoma tissue (DCIS)." (PMID 31590218, 2019). "It has been shown, that triple negative cancers have reduced expression of NER, Fanconi Anemia pathways genes, RRM1, BRCA1 and CHK1 gene when compared to other types of breast cancers." (PMID 29507678, 2018). "The relatively frequent aberrations observed in this study imply that RRM1 and RRM2B are capable of contributing to breast cancer development." (PMID 24215511, 2013). "Thus, many studies have shown that the expression and/or co-expression of several genes, such as ERCC1, RRM1, TOP1, TOP2α, TUBB3, TYMS, and GSTP1, in tumor tissues is closely related to chemoresistance and prognosis in breast cancer patients (BC)." (PMID 35204496, 2022). "This is, however, in contrast to RRM1 copy number variation, which was not significantly different between the subtypes of breast cancer." (PMID 24215511, 2013). "This study demonstrated the existence of both deletions and amplifications of RRM1 and RRM2B in primary breast tumor samples, to our knowledge unprecedented in human tumor tissue but in agreement with the frequently observed somatic changes in the genome of breast cancer cell lines." (PMID 24215511, 2013). "There is almost no copy number variation (CNV) of RRM1 and RRM2 genes in common types of cancers, whereas RRM2B displays CNV gain in more than 3% of breast cancers, liver cancers, stomach cancers and urinary tract cancers." (PMID 31637211, 2019).
liver cancer (8 papers, 2014 to 2024). An epithelial or non-epithelial malignant neoplasm that arises from the liver. "In the same cohort, the discriminative ability of liver cancer for AFP was 0.502 (95% CI: 0.418-0.586), indicating that RRM1 and RRM2 had great potential to be diagnostic biomarkers for liver cancer." (PMID 36713030, 2023). "Recent studies have demonstrated that upregulation of RRM1 has been observed in various cancers, including liver cancer." (PMID 36713030, 2023). "To assess the potential impact of the RR subunits on chemotherapy of liver cancer, we evaluated the correlations between the expression levels of RRM1, RRM2, and RRM2B and multiple drugs." (PMID 36713030, 2023). "The high expression of RRM1 and RRM2 is associated with a worse prognosis in patients with liver cancer." (PMID 36713030, 2023). "The ROC curve analysis demonstrated that the discriminative abilities of liver cancer for RRM1, RRM2, and RRM2B were 0.903 (95% CI: 0.873-0.933), 0.961 (95% CI: 0.939-0.984) and 0.767 (95% CI: 0.715-0.820), respectively." (PMID 36713030, 2023). "In HepG2 cells, dysregulation of RRM1 may contribute to the progression of liver cancer by promoting DNA synthesis and cell proliferation." (PMID 37240140, 2023). "Structurally, the RRM1–2 tandem adopts a substantially less compact arrangement when HuR is SUMOylated in positions 120 and 182, suggesting that SUMOylation may critically alter HuR conformation so as to modulate its intrinsic RNA-binding ability during liver cancer." (PMID 38507413, 2024). "Time-dependent ROC curves were adopted to compare the prognostic accuracy of RRM1, RRM2, and RRM2B in predicting the prognosis of liver cancer." (PMID 36713030, 2023). "Using the GeneMANIA database, we also identified RRM1-, RRM2-, and RRM2B-related molecules, which were also involved with liver cancer." (PMID 36713030, 2023). "The expressions of RRM1, RRM2, and RRM2B were remarkably upregulated among liver cancer tissue both in mRNA and protein levels." (PMID 36713030, 2023). "Correlation analysis also indicated that RRM1 and RRM2 had the highest correlation in liver cancer." (PMID 36713030, 2023). "Importantly, we demonstrated that RRM1 and RRM2 were not only highly expressed in liver cancer patients but also multiple liver cancer cell lines, consistent with previous studies." (PMID 36713030, 2023). "In TCGA cohort, the expression of RRM1, RRM2, and RRM2B was significantly higher in liver cancer." (PMID 36713030, 2023). "This clearly indicates that RRM1 is not subject to imprinting in hepatoblastoma, a type of liver cancer." (PMID 24915461, 2014). "Compared with AFP (positive likelihood ratio: 0.206 and negative likelihood ratio: 0.985), both RRM1 and RRM2 had greater positive likelihood ratios and less negative likelihood ratios, suggested that they might have a great diagnostic value for liver cancer." (PMID 36713030, 2023).